IL6 (interleukin 6)
Diseases named in the same sentence as IL6 in open-access papers (continued):
Sharing a sentence is not in itself a finding about the gene and the disease.
malaria (continued). "Both malaria and dengue have been associated with a strong activation of acute phase response (IL-6, TNF-α, and IL1-β) and Th1 cytokines (IFN-γ and IL-12)." (PMID 27128316, 2016). "Hepcidin was positively associated with IL-6 and IL-10 levels and with parasitaemia in subjects with mild malaria and with IFN-γ in subjects with severe malaria." (PMID 26466783, 2015). "Levels of IL-6 have already been associated with severe malaria outcomes, and jaundice has been demonstrated to be independently linked to increased levels of this cytokine." (PMID 26466783, 2015). "This indicates that protection against blood-stage malaria is associated with low production of IL-1β, TNFα, IL-6 and a high biphasic production IFNγ by the liver." (PMID 25408684, 2014). "Altogether, it is shown that both inflammatory and anti-inflammatory cytokines are produced during malaria caused by P. vivax and the levels of IL-6 and IL-10 are dependent on the parasite load." (PMID 24741587, 2014). "Plasma concentrations of IL-6 have been found to be associated with severe disease and death from malaria, and the IL6-176C allele was associated with increased expression of IL-6 in neonates and adults developing acute phase reactions." (PMID 25038626, 2014). "TNF (=TNFalpha or TNFA) and IL-6 are key mediators associated with malaria symptoms, and their levels are increased in proportion to the severity of disease." (PMID 25038626, 2014). "Participants with genotype combinations GC/CC/GG/GG and GG/CT/GG/GG (DDX39B-22/DDX39B-348/TNF-308/IL6-176) had decreased and increased risk of mild malaria, respectively, compared with asymptomatic and uninfected participants." (PMID 25038626, 2014). "Our findings establish a clear interaction between an inflammatory cytokine, IL-6, and an anti-inflammatory cytokine, IL-10, and correlation of the former with parasite load during malaria caused by P. vivax." (PMID 24741587, 2014). "Analysis of biomarker network suggests that IL-10 and IL-6 are a robust axis in malaria patients and that this interaction seems to be associated with the parasite load." (PMID 24741587, 2014). "Endotoxin acts as a potent stimulus for the release of pro-inflammatory cytokines such as TNFα, IL1 and IL6 that have been implicated in the pathophysiology of severe infectious diseases, including malaria." (PMID 23497104, 2013). "In the uncomplicated malaria group, homozygosity for the Δ22 insertion allele was associated with elevated IL-6 (p = 0.04), and at least one long GT repeat allele was associated with elevated serum TNF levels (p = 0.007)." (PMID 22336003, 2012). "Of the cytokines that were found to be associated with travel, Il-6 has been shown to often be elevated in severe cases of malaria." (PMID 22554058, 2012). "In the uncomplicated malaria group Δ22 homozygosity was associated with elevated IL-6 production (p = 0.04), and at least one long GTn allele was associated with elevated serum TNF (p = 0.007)." (PMID 22336003, 2012). "Other cytokines such as IL-1, IL-6, IL-8, IL-10 and IL-12 have been implicated in the pathogenesis of severe malaria cases compared to uncomplicated and matched healthy controls." (PMID 22480186, 2012). "In uncomplicated malaria patients, Δ22 homozygosity was associated with elevated serum IL-6 (p = 0.04), and long GT repeat alleles were associated with elevated TNF (p = 0.007)." (PMID 22336003, 2012). "The higher level of IL-6 by ECCM than ECUM observed in this study is in line with data showing that elevated plasma levels of IL-6 are associated with severe malaria." (PMID 21029292, 2011). "Elevated levels of TNF-α and IL-6 have been linked to severe malaria and poor clinical outcomes." (PMID 40061813, 2025). "Similarly, the review demonstrated that elevated IL-6 levels are associated with severe malaria, suggesting its potential as a marker of disease severity." (PMID 41194029, 2025).
malaria (continued). "These receptors initiate signalling cascades that activate nuclear factor kappa B (NF‐κB), leading to increased production of pro‐inflammatory cytokines such as TNF‐α, interferon‐gamma (IFN‐γ), IL‐1β and IL‐6, all of which are implicated in the pathogenesis of malaria." (PMID 40847608, 2025). "The concentration of IL‐6 has been associated with severe malaria and death." (PMID 38099246, 2023). "In this study, we investigated whether SNPs that were selected on the basis of interrupting IL6R and assumed to be a proxy for IL-6 signaling are associated with severe malaria case status." (PMID 36801374, 2023). "Our final limitation remains the challenge of interpreting germline variation relating to a lifetime exposure to changes in IL-6 signaling as evidence for or against the therapeutic usage of IL-6 antagonism in acute malaria or for elucidating the causal role of IL-6 in severe malaria." (PMID 36801374, 2023). "MR is a form of instrumental variable analysis whereby the genetic variation (SNPs) known to associate with an exposure (in this case, IL-6 signaling) is used to estimate the effect of that exposure on an outcome (in this case, malaria) and under certain assumptions, can provide causal estimates." (PMID 36801374, 2023). "Levels of interleukin (IL)-6 have been shown to identify cases of severe malaria and associate with severity, but it is unknown if this association is causal." (PMID 36801374, 2023). "On the other hand, symptomatic malaria occurs during the blood stages when merozoites are released in the bloodstream and results in a cascade of inflammatory cytokines such as IL-6, IL-8, IL-10, IL-1, and IL-12 that are associated with a “cytokine storm” that is implicated in disease severity." (PMID 36415655, 2022). "Indeed, interleukin (IL)-10 was shown to be a predictor of the occurrence of clinical malaria in highly endemic areas of India, while IL-6, IL-10 and IL-12 were associated with disease outcome in a non-endemic region." (PMID 35421083, 2022). "In addition, patients with malaria had increased PCT levels which were caused by an increase in proinflammatory cytokine levels such as interleukin-6 (IL-6), tumor necrosis factor-α (TNF-α), and interleukin-1β (IL-β) during infections." (PMID 36141662, 2022). "Moreover, the pro-inflammatory cytokines such as TNF-α, and IL-6 have been associated with severe malaria and death." (PMID 36548650, 2022). "The predominance of a pro-inflammatory cytokine profile in the absence of infection may be linked to the greater susceptibility of young children to severe malaria, which is determined by high IL-6 and TNF responses." (PMID 35421083, 2022). "The SNP of IL6 (-174GC) was associated with hyperparasitemia, malaria severity and IL6 level." (PMID 34698295, 2021). "Others, such as IL-6, have correlated with increased risk of clinical malaria." (PMID 31806027, 2019). "Years of studies on malaria have shown a critical role for proinflammatory cytokines in pathogenesis of the disease and high levels of proinflammatory cytokines such as TNFα, IL-6 and IFNγ have long been linked to acute phases of malaria, including cerebral malaria." (PMID 29495555, 2018). "The immune response underlying malaria-related jaundice, which is defined by high productions of interleukin (IL)-6, IL-10 and interferon (IFN)-γ, may influence hepcidin levels in hepatocytes and peripheral blood mononuclear cells." (PMID 26466783, 2015). "In the context of cGAS-STING activation, late IL-6 production was promoted in macrophages via MyD88-p38 signaling, resulting in the expansion of proinflammatory monocytes (CD11b+Ly6Chi) and the suppression of T cell proliferation, resulting in loss of the immune defense against malaria." (PMID 37781354, 2023).
malaria (continued). "Moreover, the results suggest that combinations of genotypes (including IL6-176G > C) are associated with a decreased or increased risk of developing clinical manifestations of malaria and may also influence plasma TNF and IL-6 levels." (PMID 25038626, 2014). "The highest concentrations of adipsin, C5a, TNF‐α and IL‐6 were observed in women with preeclampsia coexisting with malaria." (PMID 41536443, 2026). "The absence of this correlation in controls reflects the distinct inflammatory profiles of healthy individuals versus malaria patients, where IL-6 levels remain relatively stable." (PMID 40061813, 2025). "In accordance, our previous study demonstrated that inhibition of IL-6 trans-signaling protects against malaria-induced lethality in mice." (PMID 40243929, 2025). "Children with malaria had markedly elevated IL-6 levels, with a median of 54.2 pg/mL (IQR: 12.84 – 134.36), compared to the control group, which had a median IL-6 level of 3.3 pg/mL (IQR: 2.1 – 14.5), a difference that was significant (p < 0.001)." (PMID 40061813, 2025). "In this study, APOA1 gene polymorphisms, serum levels of APOA1, and inflammatory markers (TNF-α and IL-6) were investigated in Nigerian children with uncomplicated malaria." (PMID 40061813, 2025). "Children with malaria exhibited higher levels of IL-6 and TNF-α compared to controls, consistent with the inflammatory response characteristic of malaria infection." (PMID 40061813, 2025). "More importantly, we observed significantly higher IL-6 and IL-10 levels among individuals with previous malaria." (PMID 40726977, 2025). "STAT3 hyperactivation has also been observed in other lethal experimental malaria models, and IL-6, a key upstream activator of STAT3, is significantly elevated in severe malaria patients compared to those with non-severe malaria." (PMID 40702267, 2025). "High levels of TNF-α and IL-6 in severe malaria cases corroborate previous findings on their role in the malaria pathogenesis." (PMID 40061813, 2025). "The positive correlation between IL-6 levels and parasite counts underscores IL-6 involvement in the inflammatory response to malaria." (PMID 40061813, 2025). "Elevated IFN-γ has been associated with enhanced phagocytic activity in malaria and as a key cytokine in the activation of autoimmune atypical B cells during malaria, together with IL-6, has been related to the production of autoantibodies." (PMID 40690473, 2025). "During the early stages of malaria, the cytokine IL-6 plays a protective role, stimulating the acute phase response and supporting immune cell differentiation." (PMID 40980010, 2025). "Tumor necrosis factor-alpha and interleukin-6 levels positively correlated with parasite burden (r = 0.417, p = 0.001 and r = 0.279, p = 0.017, respectively), reflecting their roles in malaria pathogenesis." (PMID 40061813, 2025). "While IL-6 concentrations were significantly higher in malaria and typho-malaria co-infected patients, IL-10 levels were reduced in the typho-malaria group but remained elevated compared to controls." (PMID 40014608, 2025). "On the other hand, the immunohistochemistry investigation of TNF-α and IL-6 expressed strong positive reactions with pulmonary components that reflected the severity of malaria damage and lung inflammation of P. chabaudi." (PMID 40917784, 2025). "Tumor necrosis factor-alpha (TNF-α) and interleukin-6 (IL-6) are important in the pathogenesis of malaria-induced lung pathology." (PMID 40917784, 2025). "In malaria-endemic regions, children under five years of age are likely to experience dyserythropoiesis driven chiefly by inflammatory cytokines such as IL-6, TNF-α and IFN-γ." (PMID 40980010, 2025). "It has been documented that the blood-stage cycle of the malaria parasite is characterized by an upregulation of inflammatory cytokines like IL-6, IFN-γ, and TNF-α, which play a pivotal role in controlling the growth of the parasite and its elimination." (PMID 40014608, 2025).
malaria (continued). "Previous studies also indicated that increasing concentrations of IL-6 were positively correlated with disease severity in patients infected with malaria." (PMID 41552719, 2025). "In the present study, children with severe malarial anemia had significantly elevated plasma levels of TNF‐α, IFN‐ɣ, IL‐1β, IL‐6, GM‐CSF and IL‐10 than those with uncomplicated malaria, and this is in consonance with earlier findings." (PMID 39240033, 2024). "IFN-γ, IL-2, IL-5, IL-6, and IL-12 were increased in mild malaria, whereas TGF-β, TNF, IL-10, and IL-1β were particularly elevated in cerebral malaria." (PMID 38774541, 2024). "The intense sequestration exacerbates the inflammatory response and cause cytokine storm, especially increasing IL‐10, GM‐CSF, IL‐6, IL‐1β, IFN‐ɣ, and TNF‐α levels, which promotes the progression of severe malaria." (PMID 39240033, 2024). "On the contrary, TNF‐α/IL‐10 and IL‐6/IL‐10 ratios were reduced when malaria‐infected children were compared with uninfected group in Malawi." (PMID 39240033, 2024). "Activation of GPR37 through neuroprotectin D1 (NPD1) and artesunate (ARU) has been shown to decrease serum interleukin-6 (IL-6) levels in WT mice infected with LPS, Listeria, and malaria parasites, thereby mitigating inflammation and reducing mortality." (PMID 39633709, 2024). "Targeting H3K4 methylation with WDR5 antagonists can be useful in controlling excessive inflammatory TNF and IL-6 production and thereby managing the pathogenesis of severe malaria." (PMID 38316918, 2024). "A recent meta-analysis confirmed that IL-6 is prognostic for severe outcomes and differentiates uncomplicated from severe malaria." (PMID 36801374, 2023). "IL-6 levels were decreased in most studies that investigated malaria and intestinal parasite coinfections (." (PMID 36716305, 2023). "Another study showed significantly elevated IL-6 and IL-10 levels in children with severe malaria compared with uncomplicated malaria." (PMID 36668942, 2023). "The levels of nine cytokines measured in plasma revealed an increase of IL-6, IFNg, IL-22 and IL12p70 in children with symptomatic malaria compared to uninfected children." (PMID 36787308, 2023). "Supporting this, the results of animal models of IL-6 manipulation in malaria have been inconsistent." (PMID 36801374, 2023). "Our laboratory has gathered during the last decade experimental evidence, using various murine models for malaria, that the IL-6 response is critical in controlling the parasite growth by generating an effective anti-parasite immune response." (PMID 37143657, 2023). "IFN-γ, IL-6, and IL-13 levels were significantly increased in coinfections compared to malaria monoinfections, as reported by two studies." (PMID 36716305, 2023). "In human malaria, as in canine babesiosis, the IL-6 serum concentration has been found to be increased and associated with the severity of disease." (PMID 36839438, 2023). "Similar to the IL-10 levels, the IL-6 levels were seen to be higher in children with severe malaria cases than those with uncomplicated malaria." (PMID 36668942, 2023). "Other cytokines such as IL-4, IL-6, and IL-10 were also elevated in coinfections compared to malaria monoinfection." (PMID 36716305, 2023). "Given that immune response cells produce cytokines and malaria severity is associated with elevated concentrations of TNF-α, IL-6 and IL-10." (PMID 37628731, 2023). "The significantly higher levels of IL-6 and IL-10 observed in severe malarial anemia than in uncomplicated malaria suggest that these cytokines are induced during P. falciparum malarial anemia and play a role in the pathophysiology." (PMID 36787308, 2023). "Although a previous study reported co-expression of TNF and IL6 by IL-10 producing Bregs138, only a small fraction of IL-10+ Bregs co-produced IL6 during malaria, and there was minimal co-expression with TNF." (PMID 37968278, 2023).
malaria (continued). "A previous meta-analysis of 13 studies showed that patients with severe malaria had higher IL-6 levels than those with uncomplicated malaria." (PMID 36668942, 2023). "Given the importance of the pro-and anti-inflammatory balance during malaria, a comparison was performed between the ratio of the main pro-inflammatory (IL-6 and TNF-α) and anti-inflammatory (IL-10) cytokines identified in the malaria and coinfected groups." (PMID 35749690, 2022). "Second, there were a limited number of studies included in the meta-analysis that compared the differences in IL-6 levels between patients with uncomplicated and asymptomatic malaria, as well as asymptomatic malaria and healthy controls." (PMID 35396564, 2022). "In contrast to what was found for sTREM, IL-6 levels were significanty lower in the coinfected group compared to the malaria group." (PMID 35749690, 2022). "Regarding the analysis of differences in IL-6 levels between uncomplicated malaria and controls, a funnel plot showed an asymmetrical distribution of effect estimates far from the middle line." (PMID 35396564, 2022). "Higher serum levels of sTREM-1 and IL-6 were showed in malaria patients compared to healthy controls." (PMID 35749690, 2022). "Patients with uncomplicated malaria had higher mean IL-6 levels than the controls (P < 0.001, WMD = 42.86 pg/mL, 95% CI = 30.17 − 55.56 pg/mL, I2 = 100%, 17 studies)." (PMID 35396564, 2022). "It has been reported that, during immunopathogenesis of malaria, IL-6 is regulated by TNF-α and co-operates with other inflammatory mediators to control parasitemia." (PMID 35396564, 2022). "Our results also demonstrated that IL-6 serum levels increased 6.9 times in malaria patients compared to healthy individuals." (PMID 35749690, 2022). "A subgroup analysis of continents showed that mean IL-6 levels were higher in patients with uncomplicated malaria than in controls among studies conducted in Africa and Asia." (PMID 35396564, 2022). "Although an early exogenous IFN‐α/β treatment and the blockage of late IL‐6 production can enhance anti‐malaria immunity, such immunity confers only a partial resistance to N67C infections; mice died at 25–30 days post N67C infection." (PMID 35635376, 2022). "Previously, researchers discovered that TNF and Th2 group cytokines, such as IL-6 and IL-10 concentrations, were elevated in individuals with severe malaria, indicating that these cytokines play a role in the etiology of malaria disease severity." (PMID 35820892, 2022). "Here, this study reveals that cGAS‐STING signaling plays a detrimental role in regulating anti‐malaria immunity by cooperating with MyD88 to induce p38‐dependent late IL‐6 production and expanding CD11b+Ly6Chi proinflammatory monocytes." (PMID 35635376, 2022). "Significantly elevated pro-inflammatory IL-6, IL-12 have been observed in the severe-malaria group compared to age-matched healthy children." (PMID 36239109, 2022). "TNF-α is the cytokine most implicated in the development of the clinical signs of malaria, while IL-10 and IL-6 are present at high levels in patients with symptomatic malaria." (PMID 35421083, 2022). "cGAS or STING deficiency in mice markedly prolongs mouse survival during lethal malaria Plasmodium yoelii nigeriensis N67C infections by reducing late interleukin (IL)‐6 production." (PMID 35635376, 2022). "The present systematic review and meta-analysis compared the differences in IL-6 levels among several groups of patients with malaria and control groups." (PMID 35396564, 2022). "An imbalance of cytokines such as tumor necrosis factor (TNF), interleukin-6 (IL-6), IL-10, and interferon-gamma (IFN-γ) are implicated in malaria related-inflammation that induce changes in iron absorption and delocalization." (PMID 36183114, 2022). "Differences in IL-6 levels between patients with asymptomatic malaria and healthy controls were estimated using the available data of two studies." (PMID 35396564, 2022).